NAMPT (nicotinamide phosphoribosyltransferase)
Diseases named in the same sentence as NAMPT in open-access papers (continued):
Sharing a sentence is not in itself a finding about the gene and the disease.
gastric cancer (28 papers, 2011 to 2025). A primary or metastatic malignant neoplasm involving the stomach. "Additionally, extreme susceptibility to NAMPT inhibition was also seen with gastric cancer cell lines, which show markers of epithelial-to-mesenchymal transition (EMT), where this EMT subtype was associated with loss of NAPRT expression." (PMID 34068917, 2021). "In summary, we conclude that the immunosuppression of effector CD8+ T cells is restrained by inhibiting NAD metabolism through targeting NAMPT in gastric cancer, which eventually reduces the extracellular adenosine level." (PMID 35776198, 2023). "Although the Western blots showed that NAMPT was generally highly expressed in gastric cancer cell lines, there was a large variation in its expression at the mRNA level." (PMID 35776198, 2023). "The pivotal synthesis-limiting enzyme in the salvage pathway of NAD synthesis, nicotinamide phosphateribosyltransferase (NAMPT), is more highly expressed in gastric cancer than in other tumor tissues." (PMID 35776198, 2023). "We further found that the expression of NAMPT in gastric cancer tumor tissues was significantly higher than that in normal tissues after analyzing the GEO datasets GSE54129 and GSE63089, which was statistically significant." (PMID 35776198, 2023). "As previously reported in the literature, we verified that NAMPT was highly expressed in gastric cancer tissues or cells." (PMID 35776198, 2023). "USP22 also promoted gastric cancer progression and metastasis through regulating c-Myc/NAMPT/SIRT1-dependent FOXO1 and YAP signaling." (PMID 34753387, 2021). "Herein, we found that regulating NAD levels by targeting NAMPT in gastric cancer cells could alter ATP and extracellular adenosine levels, hence improving the antitumor function of CD8+ T cells in the tumor microenvironment." (PMID 35776198, 2023). "We then used RNA interference to silence NAMPT expression in gastric cancer cells." (PMID 35776198, 2023). "Because the levels of NAD+ and ATP are related to NAMPT, we hypothesize that targeting NAMPT of gastric cancer cells to regulate NAD and ATP metabolism could inhibit cell growth and achieve antitumor effects." (PMID 35776198, 2023). "In conclusion, the results of gastric cancer organoids cocultured with PBMCs indicated that targeting NAMPT in gastric cancer cells could regulate the extracellular adenosine level and inhibit the exhaustion of CD8+ T cells in the immune microenvironment." (PMID 35776198, 2023). "Therefore, this study demonstrates that NAMPT can be an effective target for gastric cancer immunotherapy." (PMID 35776198, 2023). "In this mechanism, radiochemotherapy triggers DNA damage response accompanied by elevated levels of EID3, a typical DNA repair gene, which interacts with NAMPT to promote stemness via upregulating Wnt signaling pathway, manifested by enhanced tumorsphere/tumor formation in gastric cancer." (PMID 36153608, 2022). "Moreover, the correlations of NAMPT levels in plasma with cancer invasion depth, tumor node metastasis stage, distant and lymph node metastasis were reported in a gastric cancer cohort study." (PMID 35565188, 2022). "To explore the difference between GC cell lines and GC tissues, we first verified that NAMPT expression was generally higher in gastric cancer tissues and cell lines than in normal or paraneoplastic tissues by Western blot assay." (PMID 35776198, 2023). "In gastric cancer, USP22 stabilizes the c-Myc/nicotinamide phosphoribosyltransferase (NAMPT)/SIRT1 signaling cascade, which further activates forkhead box protein O1 (FOXO1) and YAP." (PMID 33919439, 2021). "Nicotinamide phosphoribosyltransferase (NAMPT) is a key enzyme for NAD+ production from nicotinamide, and NAMPT expression by a tumor predicts a poor prognosis in colon cancer, gastric cancer, and lymphoma." (PMID 29541451, 2018).
gastric cancer (continued). "They demonstrated that NAMPT mRNA levels were notably higher in cancer tissues than in adjacent normal tissues, and protein levels were similarly elevated in three gastric cancer cell lines compared to a non-cancer cell line." (PMID 40282553, 2025). "They observed that NAMPT expression was significantly elevated in gastric cancer tissues and cell lines compared to normal or adjacent non-cancerous tissues." (PMID 40282553, 2025). "In these EMT-subtype gastric cancer cell lines, the suppression or loss of NAPRT created a synthetic lethal interaction upon the inhibition of NAMPT, as the cells lacked alternative pathways to produce NAD." (PMID 40282553, 2025). "Overall, we hypothesized that adenosine in the extracellular matrix of gastric cancer cells induces CD8+ T cell exhaustion, and that targeting NAMPT in GC cells may reverse the immune suppression of CD8+ T cells in vitro." (PMID 35776198, 2023). "To verify whether NAMPT inhibition by FK866 can suppress NAD levels in mitochondria, we used MitoTracker Red CMXRos to label the MMPs of treated gastric cancer cells and Annexin-V to label apoptotic cells." (PMID 35776198, 2023).
ovarian carcinoma (27 papers, 2014 to 2025). A malignant neoplasm originating from the surface ovarian epithelium. "RAS/PI3K pathway mutations sensitise epithelial ovarian cancer cells to NAMPT inhibition and increase the therapeutic window of a PARP and NAMPT inhibitor combination." (PMID 41419662, 2025). "BRCA1 knockdown was found to effectively increase NAMPT levels in ovarian cancer cells and primary non-BRCA1-mutated cells, suggesting a critical role for NAMPT in BRCA1-related NAD+ synthesis in ovarian cancer." (PMID 39272943, 2024). "Given that NAD+ levels are elevated in cancer cells compared with non-malignant cells due to upregulated NAD+ biosynthesis, we report high NAMPT expression is associated with poor outcomes in ovarian cancers in TCGA data." (PMID 38424218, 2024). "In ovarian cancer, increased NAMPT expression has been found to be linked to tumor lymph node metastases, invasion, advanced clinical stage, and poor survival outcomes." (PMID 39272943, 2024). "Additionally, NAMPT inhibitors suppress senescence-associated CSCs induced by platinum-based chemotherapy in ovarian cancer." (PMID 39107908, 2024). "In this study, the authors demonstrated that inhibition of NAMPT resulted in the suppression of senescence-associated cancer-stem-like cells (CSCs), which are induced by platinum-based chemotherapy and can contribute to chemoresistance in ovarian cancer." (PMID 39272943, 2024). "The combination of a PARP inhibitor and an NAMPT inhibitor initiated DNA degradation and caspase-3 cleavage, leading to apoptosis of ovarian cancer cells." (PMID 40076482, 2025). "The Cancer Genome Atlas (TCGA) proved that elevated NAMPT expression has a significant relationship with dismal prognosis in ovarian cancer patients." (PMID 40076482, 2025). "Among the few NAPRT inhibitors, 2-Hydroxynicotinic acid (2-HNA) can sensitize PH-amplified pancreatic and ovarian cancer cells to NAMPT inhibitors." (PMID 38116009, 2023). "Nevertheless, it has been demonstrated over recent years that NAMPT also plays an important role in the pathomechanism of cancer development, including ovarian cancer." (PMID 37190027, 2023). "Recent studies using NAMPT inhibitors as monotherapy in ovarian cancer cell lines have shown promising results to overcome drug resistance in certain contexts." (PMID 36849518, 2023). "NAMPT inhibition was shown to mediate this additional anticancer benefit by i) NAD-mediated inhibition of the cisplatin-induced SASP in epithelial ovarian cancer and ii) suppression of the platinum-induced senescence-associated cancer stem cells." (PMID 34068917, 2021). "We have previously demonstrated that high expression of NAMPT correlates with a substantially reduced overall survival in human ovarian cancer, suggesting that high NAMPT expression could be a prognostic factor in OV." (PMID 40280967, 2025). "Furthermore, the combination of a PARP inhibitor and an NAMPT inhibitor initiated DNA degradation and caspase-3 cleavage, leading to apoptosis of ovarian cancer cells." (PMID 40076482, 2025). "In addition, the anti-tumor effect of NAMPT inhibitors in ovarian cancer has been demonstrated in vivo." (PMID 38424218, 2024). "Furthermore, the NAMPT transcript level was higher in normal epithelial ovarian cells (HOSEpiC) than epithelial ovarian cancer cell lines derived from ascites (OVCAR-3 and SKOV-3) by 3.22- and 5.56-fold, respectively (***P < 0.001)." (PMID 36658296, 2023). "In epithelial ovarian cancer (EOC), Nacarelli and colleagues showed that platinum‐induced senescence‐associated CSCs could be suppressed by treatment with the NAMPT inhibitor FK866 (see purple box)." (PMID 34137158, 2021). "High expression of NAMPT was correlated with a significant reduction in overall survival in human ovarian cancer, suggesting that high NAMPT expression may be a prognostic factor in ovarian cancer." (PMID 38424218, 2024).
ovarian carcinoma (continued). "Therefore, in the context of PARPi resistance, NAMPT inhibition could offer a promising new option for ovarian cancer patients." (PMID 36849518, 2023). "Additionally, KPT-9274, a dual-specific inhibitor targeting PAK4 and nicotinamide phosphoribosyltransferase, effectively suppressed the growth, survival, and migration of triple-negative breast cancer 41, 42, kidney cancer 43, acute myeloid leukemia 44, and ovarian cancer cells." (PMID 39781524, 2025). "In conclusion, KPT-9274 demonstrated a promising activity against NAMPT or PAK4-driven cancer growth, suggesting it is a potential novel treatment for platinum-resistant ovarian cancer." (PMID 38424218, 2024). "Overall, our preclinical data suggest that inhibiting NAMPT and PAK4 by KPT-9274 is an effective approach to overcome platinum resistance in ovarian cancers." (PMID 38424218, 2024). "To further characterize the impact of NAMPT and PAK4 in ovarian cancer, we evaluated the ovarian cancer RNA sequencing data from TCGA." (PMID 38424218, 2024). "As such, co-targeting CD73 was shown to potentiate nicotinamide phosphoribosyltransferase (NAMPT), the rate-limiting enzyme in NAD+ biosynthesis, in a murine model of ovarian cancer." (PMID 33430239, 2021). "Next, we investigated the anti-tumor activity of the simultaneous inhibition of NAMPT (with FK866) and CD73 (with α, β-methylene adenosine 5′-diphosphate, APCP), in an in vivo human ovarian carcinoma model." (PMID 26658104, 2016). "Here, we investigated the anti-tumor potential of simultaneously inhibiting NAMPT (with FK866) and CD73 (with APCP) in an in vitro and in vivo human ovarian carcinoma model." (PMID 26658104, 2016). "To investigate the relevance of NAMPT and PAK4 in ovarian cancers, we first examined TCGA datasets." (PMID 38424218, 2024). "To do this we measured basal expression of visfatin (NAMPT) mRNA in human ovarian non-cancer (HOSEpiC and HGrC1) and human ovarian cancer (OVCAR-3, SKOV-3, and KGN) cell lines by qRT-PCR." (PMID 36658296, 2023). "In ovarian cancer models, a regulatory relationship between BRCA1 and NAMPT has been described." (PMID 32010616, 2019). "In ovarian cancer, expression of NAPRT, the key enzyme in the Preiss-Handler pathway, correlated with a BRCA-ness gene expression signature, and cells carrying these features were more sensitive to NAMPT inhibitors." (PMID 32010616, 2019). "Furthermore, both NAMPT and FK866 affected mitochondrial activity in ovarian cancer cells." (PMID 36658296, 2023).
type 2 diabetes (26 papers, 2011 to 2026). "In conclusion, we demonstrate, that circadian components of the molecular clock, namely REVERBA/B, SIRT1 and NAMPT, that are associated with mitochondrial function and metabolic health, showed lack of circadian rhythmicity in human primary myotubes from type 2 diabetic patients." (PMID 27756900, 2016). "Our results suggest that high plasma NAMPT levels are associated with CAD in subjects with type 2 diabetes and that the NAMPT rs9770242 polymorphism may be associated with CAD in some populations." (PMID 23968400, 2013). "In a high-glucose-induced zebrafish model of type 2 diabetes, chronic high glucose exposure led to a progressive decline in mitochondrial function, mediated through the activation of the miR-139-5p/NAMPT pathway." (PMID 40775221, 2025). "Edwin’s team found that GLO1 expression in the skeletal muscle of type 2 diabetic patients is regulated by NAMPT/SIRT, and supplementation with NR prevented the reduction of GLO1 expression and activity." (PMID 40775221, 2025). "This study was thus designed to investigate the pathogenic role of intracellular nicotinamide phosphoribosyltransferase (iNAMPT) and eNAMPT in promoting the development of CMD in a preclinical murine model of type 2 diabetes." (PMID 38898303, 2024). "Serum extracellular nicotinamide phosphoribosyltransferase (eNAMPT) concentrations are elevated in type 2 diabetes." (PMID 27541013, 2016). "Nicotinamide Phosphoribosyltransferase (Nampt aka Visfatin or Pbef) is an adipokine that has recently generated excitement since its expression has strong correlation with obesity and type-2 diabetes." (PMID 24339864, 2013). "In addition, several frequent polymorphisms (minor allele frequency >0.05) in the NAMPT gene were reported to be associated with a variety of physiological and pathological phenotypes including obesity, dyslipidemia, low-grade inflammation, and type 2 diabetes." (PMID 23968400, 2013). "Additionally, another study demonstrated that activation of NAMPT using the NAMPT agonist P7C3 significantly mitigated the progression of type 2 diabetes in db/db mice, while also improving skeletal muscle function." (PMID 40775221, 2025). "Specifically, we constructed a zebrafish model of T2DM to explore the molecular mechanism by which type 2 diabetes induces mitochondrial dysfunction and diabetic myopathy in skeletal muscle via NAMPT." (PMID 39859466, 2025). "This study investigated the dysregulation of key NAD+ salvage enzymes (CD38, NAMPT, and SIRT1) across albuminuria stages in type 2 diabetes (T2D)." (PMID 41470091, 2025). "These disturbances are particularly evident in conditions like aging, type 2 diabetes (T2DM), and muscle injuries, where NAMPT-mediated NAD+ salvage pathways are compromised." (PMID 39372950, 2024). "Serum concentrations of extracellular nicotinamide phosphoribosyltransferase (eNAMPT; also referred to as visfatin/pre-B cell colony-enhancing factor [PBEF]) are commonly elevated in type 2 diabetes patients, whilst raised eNAMPT levels strongly correlate with declining beta cell function." (PMID 27541013, 2016). "Aging and hypercaloric feeding compromise NAMPT- (nicotinamide phosphoribosyl transferase-) mediated NAD+ biosynthesis and may contribute to the pathogenesis of type 2 diabetes." (PMID 25918733, 2015). "In the present study we investigated associations of circulating levels of NAMPT with coronary artery disease (CAD) and related phenotypes in Brazilian subjects with high cardiovascular risk, with or without type 2 diabetes." (PMID 23968400, 2013). "Thus, P7C3-mediated NAMPT activation is critical in ameliorating diabetic skeletal muscle phenotypes in mice, and the NAMPT activator P7C3 is a potential treatment strategy for type 2 diabetes that has yet to be tested in humans." (PMID 38399441, 2024).
type 2 diabetes (continued). "Interestingly, in comparison to cultures of healthy donors REVERBA and REVERBB analysis showed no circadian rhythmicity in human primary myotubes derived from type 2 diabetes patients, and rhythmicity for SIRT1 and NAMPT was only observed in myotubes from endurance trained athletes." (PMID 27756900, 2016). "Taken together, our data indicate that NAMPT expression in subcutaneous adipocytes is not regulated by high insulin and glucose concentrations that represent common features of insulin resistance and type 2 diabetes." (PMID 21687707, 2011). "We investigated, whether or not the adipocytokine Nicotinamide phosphoribosyltransferase (Nampt) and its enzymatic product Nicotinamide mononucleotide (NMN), which has been associated with obesity and type 2 diabetes mellitus (T2DM) directly influence beta-cell survival and function." (PMID 23342086, 2013).
colon carcinoma (21 papers, 2014 to 2025). "NAMPT deficiency in macrophages reduced tumor growth in azoxymethane (AOM)/dextran sulfate sodium (DSS)‐induced colon cancer model and in xenograft model with an apparent decrease in “M2‐like” TAMs in the TME." (PMID 38308188, 2024). "We demonstrate here that NAMPT deficiency in macrophages attenuates tumor progression in colon cancer models." (PMID 38308188, 2024). "Differential expression analysis using The Cancer Genome Atlas (TCGA) and Clinical Proteomic Tumor Analysis Consortium (CPTAC) datasets revealed significantly higher NAMPT mRNA and protein levels in colon cancer tissues compared to normal tissues." (PMID 41150773, 2025). "According to the previous reports, NAMPT is a key enzyme gene in NAD+ biogenesis and has been linked to induction of CSC-like properties in colon cancer." (PMID 39107908, 2024). "More recently, Shats and colleagues reported that mycoplasma-contaminated colon cancer cells were resistant to the NAMPT inhibitor STF-118804 in culture, but also in vivo once xenografted into nude mice, and a similar effect was seen with E.coli in vitro." (PMID 34068917, 2021). "We then revealed the genes that correlate with NAPRT/NAMPT expression in colon cancer and rectal cancer using UALCAN." (PMID 31448236, 2019). "There are 305 genes that significantly correlated with NAMPT expression in both colon cancer and rectal cancer." (PMID 31448236, 2019). "We generated a variant of the human colon cancer cell line HCT116, HCT116RFK866, which exhibited primary resistance to the potent NAMPT inhibitor FK866, and was approximately 1,000-fold less sensitive to the drug than the parental HCT116." (PMID 29662658, 2018). "Acquired resistance to NAMPT inhibitors was also reported and was proposed to be mostly due to mutations in NAMPT itself, as in the case of HCT-116 colon cancer cells, which were induced to become resistant to CHS-828." (PMID 29541451, 2018). "Transplantable MC38 mouse colon cancer cells and mice carrying a specific deletion of the Nampt gene in the myeloid compartment (Namptf/f LysMCre+/−; mKO) were used to test myeloid‐specific activity of NAMPT in tumor progression." (PMID 38308188, 2024). "Considering the anti‐tumoral immunity subsequent to the inhibition of myeloid NAMPT, we next investigated its influence on CRC progression using an AOM/DSS‐induced colon cancer model." (PMID 38308188, 2024). "For example, the G217R point mutation, first detected in inhibitor-resistant HCT116 human colon cancer cells, results in a 2,500-fold shift in the 50% effective concentration (EC50) of CHS-828 relative to parental HCT116 cells, with no associated change in the level of NAMPT protein." (PMID 29662658, 2018).